FGFR1 (fibroblast growth factor receptor 1)
Description:
Tyrosine-protein kinase that acts as a cell-surface receptor for fibroblast growth factors and plays an essential role in the regulation of embryonic development, cell proliferation, differentiation and migration. Required for normal mesoderm patterning and correct axial organization during embryonic development, normal skeletogenesis and normal development of the gonadotropin-releasing hormone (GnRH) neuronal system. Phosphorylates PLCG1, FRS2, GAB1 and SHB. Ligand binding leads to the activation of several signaling cascades. Activation of PLCG1 leads to the production of the cellular signaling molecules diacylglycerol and inositol 1,4,5-trisphosphate. Phosphorylation of FRS2 triggers recruitment of GRB2, GAB1, PIK3R1 and SOS1, and mediates activation of RAS, MAPK1/ERK2, MAPK3/ERK1 and the MAP kinase signaling pathway, as well as of the AKT1 signaling pathway. Promotes phosphorylation of SHC1, STAT1 and PTPN11/SHP2. In the nucleus, enhances RPS6KA1 and CREB1 activity and contributes to the regulation of transcription. FGFR1 signaling is down-regulated by IL17RD/SEF, and by FGFR1 ubiquitination, internalization and degradation.
Synonyms: FGFR-1; BFGFR; bFGF-R-1; FLT-2; CD331; CEK; FGFBR; FLG; FLT2; HBGFR; H2; H3; H4; H5; N-SAM; ECCL; HH2; HRTFDS; KAL2; OGD
Tractability: Small molecule: an approved drug acts on it; a structure with a bound ligand is known; a high-quality ligand is known; it has a high-quality binding pocket; it belongs to a druggable protein family. Antibody: its Gene Ontology location is reachable by antibodies, with high confidence; UniProt places it where antibodies can reach, with medium confidence; UniProt predicts a signal peptide or a membrane-spanning region. PROTAC: it is named in the literature on targeted protein degradation; UniProt records ubiquitination sites on it; ubiquitination databases record sites on it; its protein half-life has been measured; a small molecule that binds it is known. Other modalities: a drug acting on it is in phase 2 or 3 trials.
Target class: Enzyme; Tyrosine protein kinase FGFR family; Protein Kinase; Kinase; TK protein kinase group
Chemical probes: AZD-4547 (high quality), CHEMBL2088092, DGY-09-192 (high quality), FIIN-1 (high quality), FIIN-2 (high quality), FIIN-3 (high quality), INFIGRATINIB (high quality), PD081496, PD084370, PD084471, PD084886, PD085217, PD134574, PD134575, PD134576, PD134577, PD134578, PD134579, PD134580, PD134581, and 1 more
Safety:
Unwanted effects reported when the protein is acted on. In parentheses: how it was acted on, where the effect was seen, and who reports it.
anaemia (inhibition; blood/bone marrow; source: Brennan et al. (2024))
AST elevations (inhibition; liver; source: Brennan et al. (2024))
decreased food intake (activation; central nervous system; source: Brennan et al. (2024))
decreased platelet count (inhibition; blood/bone marrow; source: Brennan et al. (2024))
dry eye (inhibition; ocular; source: Brennan et al. (2024))
fatigue (inhibition; source: Brennan et al. (2024))
Hyperphosphataemia (inhibition; metabolism; source: Brennan et al. (2024))
Hypoglycaemia (activation; metabolic; source: Brennan et al. (2024))
hypophosphataemia (activation; metabolic; source: Brennan et al. (2024))
keratitis (inhibition; ocular; source: Brennan et al. (2024))
reduced sweet taste (activation; source: Brennan et al. (2024))
weight loss (activation; metabolic; source: Brennan et al. (2024))
dermatologic toxicity (source: ClinPGx)
Gene: Protein-coding gene on chromosome 8 (38,400,215 to 38,468,834, reverse strand). Ensembl gene ENSG00000077782.
Subcellular location: Cell membrane; Nucleus; Cytoplasm, cytosol; Cytoplasmic vesicle
Subcellular location (Human Protein Atlas): Cytokinetic bridge; Microtubules; Mitotic spindle; Basal body; Centriolar satellite; Cytosol; Primary cilium
Pathways (Reactome):
Signal Transduction: Downstream signaling of activated FGFR1; FGFR1b ligand binding and activation; FGFR1c and Klotho ligand binding and activation; FGFR1c ligand binding and activation; FRS-mediated FGFR1 signaling; Negative regulation of FGFR1 signaling; PI-3K cascade:FGFR1; PI3K Cascade; PI5P, PP2A and IER3 Regulate PI3K/AKT Signaling; PIP3 activates AKT signaling; Phospholipase C-mediated cascade: FGFR1; RAF/MAP kinase cascade; SHC-mediated cascade:FGFR1
Disease: Constitutive Signaling by Aberrant PI3K in Cancer; Signaling by FGFR1 amplification mutants; Signaling by FGFR1 in disease; Signaling by activated point mutants of FGFR1; Signaling by plasma membrane FGFR1 fusions
Developmental Biology: Epithelial-Mesenchymal Transition (EMT) during gastrulation; Formation of paraxial mesoderm; NCAM signaling for neurite out-growth; Signal transduction by L1
Gene Ontology:
Molecular function: fibroblast growth factor binding; fibroblast growth factor receptor activity; heparin binding; identical protein binding; protein binding; protein homodimerization activity; protein tyrosine kinase activity; receptor-receptor interaction; ATP binding; protein kinase activity; transmembrane receptor protein tyrosine kinase activity
Biological process: cellular response to fibroblast growth factor stimulus; epithelial to mesenchymal transition; fibroblast growth factor receptor signaling pathway; peptidyl-tyrosine phosphorylation; positive regulation of blood vessel endothelial cell migration; positive regulation of cell population proliferation; positive regulation of endothelial cell chemotaxis; positive regulation of MAP kinase activity; positive regulation of MAPK cascade; positive regulation of neuron differentiation; positive regulation of phosphatidylinositol 3-kinase/protein kinase B signal transduction; positive regulation of vascular endothelial cell proliferation; protein autophosphorylation; cell migration; chordate embryonic development; MAPK cascade; neuron migration; phosphatidylinositol-mediated signaling; positive regulation of cell differentiation; positive regulation of phospholipase activity; protein phosphorylation; regulation of cell differentiation; skeletal system development; skeletal system morphogenesis; generation of neurons
Cellular component: plasma membrane; receptor complex; extracellular region; membrane; cytoplasmic vesicle; cytosol; nucleus
Genetic constraint (gnomAD): Loss-of-function variants: 18 observed, 97.44 expected, observed/expected ratio (o/e) 0.18, 90% interval 0.13 to 0.27. The upper end of that interval is the gene's LOEUF score, 0.27, which puts it in group 1 of 6, group 1 being the genes least tolerant of losing a copy. Missense variants: 731 observed, 1,123.4 expected, observed/expected ratio (o/e) 0.65, 90% interval 0.61 to 0.69. Synonymous variants: 448 observed, 448.08 expected, observed/expected ratio (o/e) 1, 90% interval 0.93 to 1.08.
Gene-disease validity (ClinGen):
ClinGen rates the evidence that FGFR1 causes each of these diseases.
Pfeiffer syndrome type 1 (autosomal dominant): Definitive. Pfeiffer syndrome type 1 (PS1) is a mild to moderately severe type of Pfeiffer syndrome (PS), characterized by bicoronal craniosynostosis, variable finger and toe malformations, and in most cases, normal intellectual development.
Hartsfield-Bixler-Demyer syndrome (autosomal dominant): Moderate.
osteoglophonic dysplasia (autosomal dominant): Limited. A rare skeletal disorder characterized by dwarfism, severe craniofacial abnormalities and multiple unerupted teeth.
Cancer hallmarks: invasion and metastasis (promotes); cell replicative immortality (promotes); proliferative signalling (promotes)
Homologues: Orthologues: chimpanzee FGFR1 (99% identical), macaque FGFR1 (99% identical), rabbit FGFR1 (99% identical), dog FGFR1 (99% identical), guinea pig FGFR1 (99% identical), mouse Fgfr1 (98% identical), pig FGFR1 (98% identical), rat Fgfr1 (98% identical), tropical clawed frog fgfr1 (79% identical), zebrafish fgfr1a (70% identical), zebrafish fgfr1b (68% identical), zebrafish fgfr1bl (26% identical). Paralogues in human: FGFR2 (71% identical), FGFR3 (61% identical), FGFR4 (55% identical), KDR (30% identical), FLT1 (30% identical), FLT4 (29% identical), PDGFRB (28% identical), PDGFRA (27% identical), KIT (27% identical), CSF1R (26% identical), FLT3 (24% identical), TIE1 (24% identical), and 41 more.
Diseases named in the same sentence as FGFR1 in open-access papers:
FGFR1 is named in the same sentence as 524 diseases in open-access papers, as found by Europe PMC text mining. Sharing a sentence is not in itself a finding about the gene and the disease. The quoted sentences say what the papers report.
breast cancer (349 papers, 1997 to 2026). A primary or metastatic malignant neoplasm involving the breast. "In concordance with these findings, the role of the FGFR pathway, particularly FGFR1, is implicated in cancer cell stemness in luminal A breast cancer cells, promoting palbociclib resistance through the enhancement of Akt/Erk-ER signaling." (PMID 41154409, 2025). "Equally, studies show that FGFR1 amplifications concern 11.7–14% of breast cancers and are linked to a poor prognosis." (PMID 40205008, 2025). "Aberrations in FGFR1 expression or mutations thereof are intricately linked to the onset and progression of breast cancer, underscoring its significance as a therapeutic target and prognostic marker." (PMID 38754409, 2024). "FGF signaling served as a key player in breast cancer progression, and FGFR1 and FGFR2 are known to be the most common genetic mutations." (PMID 39796710, 2024). "FGF2 binds to FGFR1 and FGFR2, and at least 10% of breast cancers harbour FGFR1 amplification, which is linked to early relapse and poor prognosis." (PMID 39251829, 2024). "FGFR1, encoding Fibroblast Growth Factor Receptor 1, emerges as a pivotal gene in breast cancer pathogenesis." (PMID 38754409, 2024). "Poor prognosis in breast cancer has been associated with elevated expression of the leptin receptor (LepR) and FGFR1 amplification, and co-expression of the FGFR1 gene and leptin protein copy number has been observed in primary breast tumours." (PMID 39251829, 2024). "In human specimens, phosphorylated FGFR1 in tumors was associated with a shorter breast cancer-specific survival after tamoxifen treatment and was also elevated in tumors from patients with a high BMI." (PMID 37608351, 2023). "FGFR1 expression in paired tissues from 426 breast cancer patients participating in the Karolinska Mammography Project for Risk Prediction of Breast Cancer (KARMA) cohort study was analyzed by immunohistochemistry." (PMID 37546410, 2023). "Further studies are needed to better understand the contribution of the FGFR1/FGF system to the molecular mechanisms behind the influence of MBD on breast cancer risk." (PMID 37546410, 2023). "The fibroblast growth factor receptor 1 (FGFR1) is amplified, mutated, or rearranged in 18% of breast cancers." (PMID 36778115, 2023). "Aberrant activation of FGF/FGFR signaling caused by FGF overexpression or FGFR1 amplification and overexpression in ER+ breast cancer cells is associated with estrogen-independent cell proliferation, metastasis and reduced distant metastasis-free survival." (PMID 35846378, 2022). "The FGFR pathways, particularly FGFR1-4, are overactivated in breast cancer and other malignancies and are implicated in cancer progression." (PMID 36358806, 2022). "FGFR1 signalling associated with ER in the nuclei of breast cancer cells regulates the transcription of ER-dependent genes, contributing to mechanisms of resistance in ER-positive samples." (PMID 35193394, 2022). "The FGFR1 gene on the 8p11–12 chromosomal region is mutated in around 15% of breast cancer, more specifically in 27% of HER2-positive patients, in 23% of ER-positive patients and in 7% of TNBC patients." (PMID 35193394, 2022). "FGFR-1 upregulation has been associated with endocrine therapy resistance in breast cancer patients." (PMID 35688802, 2022). "The clinical relevance of mRNA and protein expression of FGFR1 and its associated genes were also evaluated in mouse embryonic fibroblasts (MEFs) and breast cancer cell line (MDA-MB-231)." (PMID 34722544, 2021).
breast cancer (continued). "Analysis of 1875 breast tumor samples showed that FGFR1 8p11-12 amplification occurs in 10.5% of breast cancers, associated with estrogen receptor (ER) expression and lobular breast cancer, and in 8.9% of a cohort of 595 breast cancer tumors." (PMID 34068954, 2021). "Studies are underway to identify FGFR1-linked gene set(s) to devise effective breast cancer treatment options." (PMID 34722544, 2021). "Analysis of publicly available breast cancer expression profiles revealed that high expression of both FGFR1 and HGF were associated with poor relapse-free survival (RFS) specifically in basal tumours." (PMID 33772015, 2021). "The aim of the current study was to identify FGFR1-linked gene sets to devise effective breast cancer treatment options." (PMID 34722544, 2021). "What is more, allelic loss and amplification of FGFR1 can predict chemo‐ and radiotherapy response in breast cancer." (PMID 33655556, 2021). "FGFR1 amplifications in breast cancer are associated with lower rates of five-year disease-free survival, overall-survival and resistance to endocrine therapy." (PMID 34068954, 2021). "FGFR1 is a known poor prognostic marker also associated with poor survival in breast cancer patients." (PMID 34722544, 2021). "The current study provides new FGFR1-linked biomarkers, which suggest novel treatment options for improving the prognosis of breast cancer patients." (PMID 34722544, 2021). "FGFR1 can also undergo gene amplification and translocation, and elevated expression of FGFR1 is associated with decreased clinical outcomes of breast cancer patients." (PMID 33479246, 2021). "The locus encoding FGFR1 is amplified in 14% of breast cancer patients, and FGFR1 expression can be further upregulated through the process of epithelial–mesenchymal transition, a key driver of both drug resistance and metastasis." (PMID 33033382, 2020). "Independently, high FGFR1 protein expression or high LepR protein expression is implicated in the poor prognosis of breast cancer patients." (PMID 33019728, 2020). "Conversely, an FGFR1-associated SNP (rs17182023) has been linked to a low FGFR1 protein expression and a reduced breast cancer risk." (PMID 33081025, 2020). "FGFR1 amplifications have been reported to be present in 10% of all breast cancers and increased protein expression of FGFR1 is associated with having a poorer clinical prognosis, and greater tumor size." (PMID 33019728, 2020). "In this study, we leverage public gene expression datasets to evaluate the associations between FGFR1, leptin, and the leptin receptor (LepR) in breast cancer." (PMID 33019728, 2020). "In both ER+ and ER− breast cancers, there was a positive association between FGFR1 mRNA, and LepR mRNA, although ER- tumors had significantly higher leptin mRNA compared to ER+ tumors." (PMID 33019728, 2020). "Collectively, these data demonstrate a positive association between FGFR1, leptin, and the LepR in human primary breast cancer and a much weaker association in metastatic tumors." (PMID 33019728, 2020). "Analyzing publicly available databases, we then showed that FGFR1 is the most frequently amplified receptor of the FGFRs family along with its association with shorter survival rates in breast cancer patients." (PMID 30866584, 2019). "FGFR1 amplification and/or mRNA overexpression is present in around 15% of ER+ breast cancer and has been associated with early relapse following adjuvant tamoxifen and with poor survival in ER+ breast cancer." (PMID 30914635, 2019). "Our results demonstrate that FGFR1 alternative splicing variants FGFR1α and FGFR1β function differently in breast cancer." (PMID 30713601, 2019). "Over the past years, alternative splicing events have been discovered in FGFR1 which were implicated in genesis and development of malignant tumors, including breast cancer." (PMID 30713601, 2019). "Previous studies have demonstrated FGFR1 activation caused a loss of cell polarity in breast cancers." (PMID 30931252, 2019).